SMO (smoothened, frizzled class receptor)
Diseases named in the same sentence as SMO in open-access papers (continued):
Sharing a sentence is not in itself a finding about the gene and the disease.
meningioma (continued). "In 2013, Clark and colleagues first described an association between WHO grade, histological subtype and the anatomical location of meningiomas with distinct molecular features, including mutations in TRAF7, KLF4, AKT1, SMO and NF2." (PMID 39273576, 2024). "Further frequent non-NF2 driver mutations in meningiomas include oncogenic mutations in TRAF7, KLF4, AKT1 and SMO, which are all mutually exclusive to NF2 mutations." (PMID 39273576, 2024). "NF2 wild-type meningiomas frequently harbor mutations in TRAF7, KLF4, AKT1, PIK3CA, and SMO and are enriched in skull-base meningiomas." (PMID 38571886, 2024). "In 2013, two separate landmark studies utilized whole genome and whole exome sequencing to uncover novel mutations in non-NF2 meningiomas including TRAF7 (TNF receptor associated factor 7), KLF4 (Krüppel-like factor 4), AKT1, and SMO (Smoothened)." (PMID 36840836, 2023). "Similar observations have been made in meningioma cells, which display primary cilia and can enrich activating forms of SMO within them but are unable to transduce downstream SHH pathway activation." (PMID 37830570, 2023). "Based on this, SMO inhibitors, sonidegib and vismodegib, are currently being investigated as a treatment for meningiomas (NCT03434262 and NCT02523014)." (PMID 36672431, 2023). "Indeed, it seems reasonable to assume that at least part of the meningioma cases previously believed to be caused by yet unrecognized genetic factors might in fact contain BRAF/NF2/PIK3CA/SMO mutations at frequencies inferior to the limits of traditional detection methods." (PMID 38259646, 2023). "Important driver mutations specifically associated with meningioma pathology (including NF2, TRAF7, SMO, PIK3C2B and AKT1) that were identified in the tissues were consistently found in spheroids." (PMID 38102708, 2023). "Molecular sequencing has also revealed potential therapeutic targets in meningioma including SMO, AKT/PI3K, and BAP-1." (PMID 38066633, 2023). "In our study, we identify overexpression of pathway ligands as a route to Hh signaling activation in meningiomas, a mechanism that occurs upstream of SMO and is thus predicted to respond to Vismodegib." (PMID 37805627, 2023). "MC ben-1 meningiomas were enriched in NF2 mutations while the MC ben-2 subgroup was enriched in non-NF2 mutations including TRAF7, AKT1, KLF4, and SMO." (PMID 36840836, 2023). "SMO is a member of the Hedgehog (Hh) signaling pathway and is present in a small percentage of meningiomas (5%), specifically the meningothelial subtype." (PMID 37898750, 2023). "NGS has led to the identification of novel driver gene mutations in meningioma in addition to NF2, including SMO, PI3KCA, TRAF7, KLF4, AKT1, POLR2A, and SMARCE1." (PMID 38066633, 2023). "SMO, PI3KCA and AKT1-mTOR mutations are typically found in WHO grade 1 meningiomas with a high rate of recurrence." (PMID 35892898, 2022). "TRAF7 is also one of four genes including KLF4, AKT1, and SMO, likely to be mutated in non-NF2 mutated meningiomas found at the skull base." (PMID 36686824, 2022). "Meningioma‐relevant mutations were present in 90/126 (71.4%) specimens including NF2, TRAF7, KLF4, SMO, AKT1,TERT promotor, ARID,SUFU, and PIK3CA mutations in similar frequencies compared to previous studies." (PMID 35213082, 2022). "The only trial to enroll meningioma patients alone is A071401, a Phase 2 trial of SMO/AKT/NF2/CDK inhibitors in patients with progressive meningiomas harboring corresponding mutations in the respective signaling pathway (NCT02523014)." (PMID 35936751, 2022). "Noteworthy, none of the cases had gene mutations typically observed in skull base meningiomas and involving AKT1, PIK3CA and SMO, while one case had co-occurring NF2 and SMARCB1 mutations previously found in sagittal meningiomas." (PMID 35049691, 2022).
meningioma (continued). "Compared to meningiomas with AKT1 mutations, SMO-mutated olfactory groove meningiomas had higher recurrence rates, and when compared to AKT1-mutated or wild type meningiomas, SMO-mutated anterior skull base meningiomas had significantly larger tumor volume." (PMID 36686824, 2022). "AKT1, KLF4, SMO, or POLR2A mutations were significantly more frequent in meningiomas of skull-base lesions than in those of supra-tentorial lesions (p = 8.3 × 10–11)." (PMID 33772057, 2021). "Apart from NF2 alterations in sporadic meningiomas, various oncogenic mutations in KLF4, SMO, TRAF7, PIK3CA, AKT1 and POLR2A are also found to be clinically actionable genetic events in meningiomas." (PMID 34722286, 2021). "Low-grade meningiomas can also present other genetic alterations, particularly affecting SMO, TRAF7, KLF4 AKT1 and PI3KCA." (PMID 34679551, 2021). "Another four genes (PNMA6A, TIGD1, PTEN, and SMO) were found to be altered in >10% of all WHO grade 1 meningiomas investigated, while the remaining CREG2, EEF1A1, and POLR2A genes were recurrently altered in a minority (<10%) of cases." (PMID 34868937, 2021). "PIK3CA mutations are found in 4–7% of meningiomas and often cooccur with TRAF7 mutations but are exclusive of NF2, AKT1, and SMO mutations." (PMID 33801089, 2021). "Mutations in TRAF7 have been identified in nearly one-fourth of meningiomas, while mutations in AKT1 and SMO have lower prevalence and are associated with higher grade NF2 wild-type tumors." (PMID 34300316, 2021). "In particular, AKT1, KLF4, SMO, or POLR2A mutations were significantly more frequent in meningiomas of paraxial mesodermal origin than in those of neural crest (p = 1.7 × 10–10) and dorsal mesodermal origin (p = 3.0 × 10–4)." (PMID 33772057, 2021). "We comprehensively evaluated associations among tumor location, pathological diagnosis (histological type), and genetic alterations including AKT1, KLF4, SMO, POLR2A, and NF2 mutations and 22q deletion in 269 meningioma cases." (PMID 33772057, 2021). "From the embryological viewpoint, we found that the meningiomas harboring AKT1, SMO, KLF4, or POLR2A mutations were significantly associated with paraxial mesodermal origin." (PMID 33772057, 2021). "In turn, the frequency of non-synonymous genetic variants that affected individual genes in these three cytogenetic subgroups of meningiomas revealed different mutational profiles among them for the NF2, SMO, and POLR2A genes." (PMID 34868937, 2021). "Based on these molecular features, several clinical trials in NF-2 wild type meningiomas, including targeted therapy for actionable mutations in PIK3CA, SMO, and AKT1 are ongoing (NCT02523014)." (PMID 33611710, 2021). "The development of a molecularly driven trial of patients given targeted therapy based on their AKT1, SMO, and NF2 pathogenic variant status is an ideal example of the future for clinical trials in patients with meningioma (NCT02523014)." (PMID 33262459, 2021). "A second subgroup contained AKT1 (n = 26), PIK3CA (n = 14) and SMO (n = 7) mutant skull-based meningiomas, and a third mixed subgroup included 237 meningiomas with a heterogeneous spectrum of low frequency and non-recurrent alterations." (PMID 33087175, 2020). "This new era began with the publication of two landmark genetic sequencing studies in 2013, in which AKT1, SMO, TRAF7 and KLF4 were identified as frequently mutated genes in skull base, WHO grade 1 meningiomas." (PMID 33087175, 2020). "Genomics studies have confirmed the importance of mutations such as NF2, TRAF7, KLF4, AKT1, SMO, PI3KCA, and POLR2A in the occurrence and development of meningiomas." (PMID 32974188, 2020). "A second subclass within this group contained AKT1 (n = 26), PIK3CA (n = 14) and SMO (n = 6) mutant meningiomas (total n = 46)." (PMID 33087175, 2020). "Grade III meningioma are less likely to have TRAF7, AKT1, or SMO mutations, and exhibit genomic instability in the form of increased copy number variation." (PMID 32742192, 2020).
meningioma (continued). "Our results were consistent with earlier studies that reported mutations in NF2, SMO, and AKT1 genes in atypical meningiomas, and we also observed mutations in MYBL2, a gene that was recently discovered." (PMID 32742192, 2020). "In the present study, all the sample groups had mutations in the meningioma-driver genes such as NF2, AKT1, SMO, TRAF7, and KLF4." (PMID 32742192, 2020). "Next, we focused on the most common genetic alterations reported so far in meningiomas, including the NF2, SMARCB1, as well as TRAF7, AKT1, SMO, KLF4, PIK3CA, and TERT in non-NF2 mutated meningiomas." (PMID 31470906, 2019). "Recently, alterations in other oncogenic genes such as TRAF7, AKT1, KLF4, PIK3CA, SMO, and DMD have also been implicated in meningioma etiology." (PMID 31191822, 2019). "To date, loss of the chromosomal region 1p and mutations in SMO, AKT1 and the TERT promoter are independent (cyto-)genetic predictors for meningioma recurrence." (PMID 31139260, 2019). "Among the meningiomas, the most common mutations were in NF2 (59/71), PIK3CA (22/71), FGFR3 (13/71), SMO (11/71) and AKT1 (10/71), with Tertp (1/71) mutations the least frequent." (PMID 31565188, 2019). "To date, loss of the chromosomal region 1p and mutations in SMO, AKT1 and the TERT-promoter are known as independent predictors for meningioma recurrence." (PMID 31139260, 2019). "Exclusive of TRAF7, AKT1, PIK3CA, KFL4, and SMO, mutations in POLR2A, which encodes DNA-directed RNA polymerase II subunit RPB1, are found in 6% of meningiomas." (PMID 31970090, 2019). "Next, we focused on the most prevalent genetic alterations reported in meningiomas so far, including NF2, SMARCB1, as well as TRAF7, AKT1, SMO, KLF4, PIK3CA, and TERT in non-NF2 mutated meningiomas." (PMID 31470906, 2019). "Mutations in the hedgehog pathway signaling member smoothened (SMO, 7q32.1) have been observed in 5.5% grade I meningioma and they are either L412F or W535L." (PMID 30082628, 2018). "SMO mutations, which activate Hedgehog signaling, were identified in 5% of non-NF2 mutated meningiomas." (PMID 30279357, 2018). "Meningothelial and transitional meningiomas are more frequently seen in SMO, TRAF7/AKT1, and TRAF7/KLF4 mutant tumors." (PMID 30082628, 2018). "The tumor location changes according to the mutation type: anterior fossa, median middle fossa, or anterior calvarium for TRAF7/AKT1 and SMO mutated meningiomas; lateral middle fossa and median posterior fossa for TRAF7/KLF4-mutated meningiomas." (PMID 30279357, 2018). "We also performed Sanger sequencing to check for the presence of mutations previously reported in meningioma driver genes, including regions of NF2, AKT1, TRAF7, KLF4, SMO, and the TERT promoter." (PMID 28552950, 2017). "We found that the PI3K/mTOR/AKT and SMO pathways were activated in 75% of human meningioma cell lines." (PMID 28552950, 2017). "Other mutations associated with meningiomas (ARID1A, SMO and TRAF7) were also restricted to sporadic meningiomas, suggesting that radiation therapy induces tumorigenesis through a different set of genetic alterations to those of sporadic meningioma." (PMID 28775249, 2017). "Oncogenic mutations in PIK3CA are observed in ~7% of non-NF2-mutant meningiomas, and occur mutually exclusive of AKT1 and SMO mutations, although they frequently co-occur with TRAF7 mutations." (PMID 27458586, 2016). "A clinical trial targeting AKT1 and SMO is currently underway for progressive meningiomas (NCT02523014)." (PMID 27458586, 2016). "Next-generation sequencing has characterized recurrent somatic mutations in NF2, TRAF7, KLF4, AKT1, SMO, and PIK3CA, which are collectively present in ~80% of sporadic meningiomas." (PMID 27458586, 2016). "Such an approach is now feasible in meningioma with the recent identification of AKT1, SMO, and PIK3CA mutations, which opens the door for targeted pharmacotherapeutics in ~20% of grade I meningiomas." (PMID 27458586, 2016).
meningioma (continued). "Mutations in the genes AKT1, SMARCB1, and SMO are rare in cases of atypical meningiomas, and mutations in the genes KLF4 and TRAF7 are associated with an indolent clinical behavior, thus making these meningiomas have a low risk of progression." (PMID 39202270, 2024). "Interestingly, meningiomas with mutations in TRAF7, KLF4, AKT1 and SMO, as well as POLR2A, were later described by Nassiri and colleagues to have a more favorable patient prognosis compared to other genetic driver mutations." (PMID 39273576, 2024). "Furthermore, several typical meningioma locations have distinct related genomic markers (e.g., anterior skull base: SMO, AKT1E17K, TRAF7; central skull base: AKT1, KLF4, TRAF7, POLR2A, Convexity: NF-2, LOH chromosome 22, BAP1)." (PMID 38017560, 2023). "Other checkpoint proteins expressed include PD-L2 and B7-H3 in meningiomas with alterations in the PI3K/AKT/mTOR pathway genes, CTLA-4 in CD3+ T cells in atypical meningiomas with PIK3CA or smoothened, frizzled class receptor (SMO) mutations, and the cancer/testis antigen NY-ESO-1." (PMID 37366884, 2023). "Lastly SMO mutations were found in a minority of meningiomas without alterations in the other genes above." (PMID 36840836, 2023). "SMO mutations which activate Hedgehog signaling were identified in 5% of non-NF2 mutant meningiomas and NF2 and/or chromosome 22 loss were more likely to be atypical meningiomas." (PMID 36033542, 2022). "Moreover, some actionable mutations, including SMO, AKT1, and PIK3CA, regulate meningioma growth and are under investigation in clinical trials." (PMID 35565385, 2022). "Since 40-60% of sporadic meningiomas have a loss of NF2 expression, meningiomas can be molecularly categorized into NF2 mutants and non-NF2 mutants, with the latter predominantly comprised of TRAF7, KLF4, AKT1, SMO, and P13K mutations." (PMID 35712492, 2022). "Irrespective of the histological grade, most meningiomas (55%) exhibit NF2 alterations, while NF2 wild-type meningiomas may harbor mutations in TRAF7, KLF4, PIK3CA or SMO." (PMID 35049691, 2022). "According to the 2021 WHO brain tumor classification scheme, convexity and the majority of spinal meningiomas have similar molecular findings (loss of chromosome 22q and/or NF2 mutations), while skull base meningiomas demonstrate different mutations (AKT1, TRAF7, SMO, and PIK3CA)." (PMID 36179256, 2022). "SMO- and AKT-1-mutated meningiomas have shown to recur more frequently, compared with meningiomas lacking SMO and AKT1 mutations." (PMID 35565385, 2022). "SMO and v-akt murine thymoma viral oncogene homolog 1 (AKT1) can lead to the activation of PI3K–AKT–mTOR pathway; it is relatively common and is associated with meningiomas localized in the skull base and with genomic stability." (PMID 34679551, 2021). "In NF2 wild-type meningiomas, mutations in TRAF7, KLF4, AKT1, and SMO were noted." (PMID 34778063, 2021). "Notably, non-synonymous genetic variants of SMO and POLR2A were restricted to diploid meningiomas, whereas NF2 mutations were only found among tumors that showed -22/22q─ (with or without a complex karyotype)." (PMID 34868937, 2021). "Interestingly, genetic abnormalities in meningiomas are different in relation to the location and the type of the lesion: in fact, SMO and AKT1-MTOR mutations are quite common in non-NF2, genomically stable meningiomas of the skull base." (PMID 32244473, 2020). "We did observe meningioma-related mutations in oncogenic AKT1, SMO, TRAF7, and NF2 gene." (PMID 32742192, 2020). "In this study, the presence of AKT1 and SMO mutations along with mutated MYBL2, both in the NF2-mutant primary atypical meningioma tumor and the derived cell line, proved that the meningioma-derived primary cell line had retained the genetic signature of the original tumor." (PMID 32742192, 2020).
meningioma (continued). "While KLF4 or AKT1 mutations almost always co-occurred with TRAF7 mutations, they did not occur together; SMO-mutated meningiomas all harbored the activating L412F mutation." (PMID 31652973, 2019). "In meningioma, TRAF7 mutations can co-occur K409Q mutation in KLF4, a transcription factor known for its role in inducing pluripotency, and are mutually exclusive with NF2 mutations, chromosome 22 loss, and SMO mutations and was less common in HGMs." (PMID 30082628, 2018). "Drugs targeting SMO or AKT1mutations6,7 in meningiomas are being studied." (PMID 29391485, 2018). "A better understanding of the molecular drivers of tumor progression and recurrence, such as the roles of NF2, SMO, AKT1, TRAF7, and KLF4 mutations, will facilitate the development of targeted therapies, potentially improving outcomes for patients with atypical and anaplastic meningiomas." (PMID 41007735, 2025). "The most common genetic aberration in meningiomas is functional loss of NF2 and occurs in both low- and high-grade meningiomas, whereas NF2-wildtype meningiomas are enriched for recurrent mutations in TRAF7, KLF4, AKT1, PI3KCA, and SMO and are more frequently benign." (PMID 38571886, 2024). "SMO mutations occur in about 5% of meningiomas which do not show alterations in NF2, AKT1 and KLF1." (PMID 36181606, 2023). "TRAF-7 mutated meningiomas demonstrated elevated levels of programmed death ligand-1 (PD-L1), the major ligand for the programmed death checkpoint pathway, while PD-L2 is highly expressed in PI3K/AKT/mTOR pathway mutations and CTLA-4 was frequently expressed in PIK3CA and SMO mutated tumors." (PMID 36033542, 2022). "Overall, WHO grade 1 meningiomas harbored numerous and heterogeneous genetic variants, which most frequently affected the NF2 (47%) gene and to a less extent the PNMA6A (22%), TIGD1 (16%), SMO (13%), PTEN (13%), CREG2 (9%), EEF1A1 (6%), POLR2A (6%), ARID1B (3%), and FAIM3 (3%) genes." (PMID 34868937, 2021). "Moreover, over-expression of an oncogenic allele of the Hedgehog pathway activator Smoothened (SMO) promotes arachnoid hyperproliferation in mice, but does not cause meningiomas of the same size or number as inactivating alleles of Nf2." (PMID 32690089, 2020). "However, mutations in TRAF7 can be present in isolation, though often they can co-occur with KLF4, AKT1, or PIK3CA mutations, whereas mutations in SMO and POLR2A are usually mutually exclusive Interestingly, the meningiomas arising from SMO and AKT1-MTOR aberrations often arise in the skull base." (PMID 33194703, 2020). "In addition to the established association of meningioma with pathogenic aberrations in the tumour suppressor gene NF2, genomic analyses have identified genes including TRAF7, KLF4, AKT1, SMO, PIK3CA and POLR2A to possess recurrent mutations in low grade non-NF2 mutant meningioma." (PMID 33167358, 2020). "Interestingly, recent reports have identified SMO mutations in meningiomas lacking NF2 mutations, which further supports the potentially relevant role of this pathway in the development of at least some meningiomas." (PMID 25965831, 2015). "Other genetic alterations, exclusive of NF2 that are reported in sporadic adult meningiomas, include TRAF7, SMO, KLF4, AKT1 and PIK3CA." (PMID 39612013, 2024). "A meningioma is a tumor that originated from the meninges with alterations in NF2, AKT1, TRAF7, SMO, and PIK3C, and most meningiomas are benign." (PMID 38540119, 2024). "Few of these biomarkers are being studied in clinical trials to develop targeted personalized therapies, including a phase II trial (NCT02523014) to investigate drugs in AKT1-mutant, SMO-mutant, or NF2-mutant meningiomas." (PMID 38001599, 2023). "However, a recent publication suggests that SMO mutations may not be associated with an activation of the SHH pathway in preclinical models of meningioma, potentially challenging the efficacy of vismodegib in these tumors." (PMID 36181606, 2023).